SNORA81 (small nucleolar RNA, H/ACA box 81)
Synonyms: HBI-61
Gene: Small nucleolar RNA gene on chromosome 3 (186,786,675 to 186,786,852, forward strand). Ensembl gene ENSG00000221420.
Gene Ontology:
Biological process: RNA processing
Cellular component: nucleolus
Homologues: Orthologues: chimpanzee SNORA81 (100% identical), macaque SNORA81 (98% identical), rabbit SNORA81 (97% identical), guinea pig SNORA81 (94% identical), pig SNORA81 (93% identical), mouse Snora81 (90% identical), rat Snora81 (90% identical), mouse Gm22519 (89% identical).
Diseases named in the same sentence as SNORA81 in open-access papers:
SNORA81 is named in the same sentence as 3 diseases in open-access papers, as found by Europe PMC text mining. Sharing a sentence is not in itself a finding about the gene and the disease. The quoted sentences say what the papers report.
ovarian carcinoma (1 paper, 2022). A malignant neoplasm originating from the surface ovarian epithelium. "To understand the mechanism by which SNORA19 and SNORA81 affect cell growth we examined the impact of their knockdown on cell survival and proliferation rate, in different ovarian cancer model cell lines featuring different levels of snoRNA expression and rRNA modification." (PMID 35047824, 2022). "Interestingly, the knockdown of two examples of these HGSC-associated snoRNAs, SNORA81 and SNORA19, inhibited the proliferation and induced apoptosis of three different model ovarian cancer cell lines consistent with their upregulation in the aggressive HGSC." (PMID 35047824, 2022).
SNORA81 also shares sentences with these, for which no sentence is quoted: asthma (1 paper); cancer (1).